MIF (macrophage migration inhibitory factor)
Diseases named in the same sentence as MIF in open-access papers (continued):
Sharing a sentence is not in itself a finding about the gene and the disease.
tumor (continued). "Macrophage migration inhibitory factor (MIF) is a pleiotropic proinflammatory cytokine that is abnormally expressed in various solid tumors and is known to promote tumor progression and metastasis." (PMID 41191140, 2025). "Once tumors began to grow, the growth rate was similar, which raises questions related to stromal MIF effects on delaying early tumor survival, establishment, or growth." (PMID 41122966, 2025). "MIF enhances the release of cytokines, chemokines, and angiogenesis factors, contributing to tumor vascularization and angiogenesis." (PMID 41159021, 2025). "CCL4, CXCL8, and MIF have received considerable attention for their roles in tumor proliferation, differentiation, angiogenesis, and tumor progression." (PMID 40092701, 2025). "The study found that the MIF-(CD74+CD44) complex play a significant role in tumor development by promoting immune cell migration and activation." (PMID 40110199, 2025). "This metabolic reprogramming triggers up-regulation of macrophage MIF secretion from tumor cells, resulting in amplified accumulation of CD68+ macrophages." (PMID 41355895, 2025). "These analyses of single-cell sequencing data suggest that tumor cells predominantly interact with myeloid cells through the secretion of MIF in the human HNSCC." (PMID 39891284, 2025). "To analyze the role of MIF signaling in the CRC tumor microenvironment, we calculated the input and output signaling intensities of the MIF pathway for each cell subpopulation." (PMID 40589755, 2025). "MIF is consistently overexpressed in both tumor tissues and sera of patients with primary sporadic CRC." (PMID 40835826, 2025). "Upon binding to (CD74+CD44) complexes, extracellular MIF triggers downstream signaling that exacerbates inflammation, tumor growth, and metastasis." (PMID 40948800, 2025). "Addressing these challenges requires innovative strategies that account for tumor heterogeneity and the intricate functions of MIF." (PMID 41159021, 2025). "Signaling flow and network differences highlighted a significant augmentation of MIF signaling between epithelial cells and myeloid cells in tumor tissue in contrast to that in the normal mucosal." (PMID 39891284, 2025). "In tumor-immune cell crosstalk, macrophage migration inhibitory factor (MIF) was identified as a pivotal signaling molecule." (PMID 40861802, 2025). "Special focus is given to MIF interplay with several oncogenic pathways, modulation of the tumor microenvironment, and its dual role in both autocrine and paracrine signaling within tumors." (PMID 41159021, 2025). "The authors’ conclusions dovetail with those of several recent studies that have used orthogonal approaches to identify MIF as a target of tumor aggressiveness and immune resistance." (PMID 40131169, 2025). "MIF has been known to mediate tumor-macrophage crosstalk in other cancers, such as NSCLC, suggesting a potential role in modulating S1P-driven effects in CRC." (PMID 40589755, 2025). "Mechanistically, CDK4/6i enhances the accumulation and activation of M1 TAMs and promotes the M2 to M1 polarization via augmented interaction of the macrophage migration inhibitory factor (MIF)-CD44/CD74 axis between tumor cells and macrophages." (PMID 41082324, 2025). "Therapeutically, targeting MIF shows promise in overcoming resistance and suppressing tumor growth in CRC." (PMID 41159021, 2025). "Utilizing the immune-competent AOM/DSS mouse model, which closely mimics human CRC progression, we selectively depleted epithelial MIF during tumorigenesis at established tumor stages." (PMID 40835826, 2025). "Key inflammatory mediators within the tumor microenvironment include cytokines such as macrophage migration inhibitory factor (MIF), tumor necrosis factor-alpha (TNF-α), and interleukin-6 (IL-6)." (PMID 41011005, 2025). "According to CellChat analysis, metastatic dissemination cells interact with TAMs in the tumor microenvironment via signaling pathways such as MIF." (PMID 40303346, 2025).
tumor (continued). "During tumorigenesis, MIF protein levels are often elevated in tumor cells through chaperone-mediated stabilization." (PMID 40835826, 2025). "Non-hierarchical clustering revealed increased expression of macrophage migration inhibitory factor (MIF) in the tumour ROIs, highest in the lymph node metastases, suggesting involvement of inflammatory macrophages in metastasis development and ICI evasion." (PMID 41168392, 2025). "Taken together, these results suggest that reduction of tumor-derived MIF secretion enhances CAR-T cell efficacy both in vitro and in vivo." (PMID 39908652, 2025). "Elevated MIF expression is observed in many tumor types, contributing to cancer progression and poor prognosis." (PMID 41472252, 2025). "Preclinical studies suggest that MIF inhibition can sensitize tumors to immunotherapy by altering the tumor microenvironment." (PMID 41159021, 2025). "Previous studies have highlighted MIF as a key immunosuppressive pathway in the tumour microenvironment, reinforcing the significance of these identified interactions." (PMID 40736341, 2025). "Functional crosstalk between metastatic dissemination cells and LA-TAMs within the tumor microenvironment was mediated through MIF signaling, underscoring the critical involvement of LA-TAMs in shaping the pro-metastatic immunosuppressive microenvironment." (PMID 40303346, 2025). "This highlights MIF as a tumor-specific vulnerability and suggests that anti-MIF therapies are likely to be well tolerated, with are also shown by minimal toxicity to patients." (PMID 40835826, 2025). "The results showed that MIF expression was significantly elevated in CRC tumor tissues compared to normal tissues." (PMID 40589755, 2025). "MIF’s complex and sometimes paradoxical roles in tumor biology, as well as the limitations of current therapeutic approaches, present important hurdles that must be addressed to fully realize its clinical potential." (PMID 41159021, 2025). "In summary, aberrant MIF level presents a tumor-specific vulnerability that can be exploited therapeutically in CRC." (PMID 40835826, 2025). "Coculture conditions increased the secretion of the tumorigenic proteins BAFF, IL‐1ra, G‐CSF, Flt‐3 ligand, and MIF, which all support tumor proliferation and/or progression." (PMID 40277152, 2025). "MIF signaling was particularly robust between OS cells and macrophages, indicating a feedback loop wherein tumor-derived and macrophage-derived MIF mutually reinforce inflammatory signaling, angiogenesis, and macrophage recruitment." (PMID 40895569, 2025). "Gui-Qi Zhu and colleagues demonstrated that MIF promotes the expansion of immunosuppressive myeloid-derived cells, accelerating tumor progression and dampening antitumor immunity." (PMID 41127012, 2025). "Anti–PD-1 and anti-MIF combination therapy increases tumor infiltration of type 1 conventional dendritic cells while decreasing tumor-associated macrophages and angiogenesis." (PMID 41122966, 2025). "Our experiments showed that CD74 activated the ERK1/2-MAPK signaling pathway by binding to MIF, promoting the proliferation and survival of tumor cells." (PMID 41275376, 2025). "In line, calculation of the total tumor area confirmed that a MIF depletion reduced the growth of established tumors." (PMID 40835826, 2025). "In contrast, tumor cells showed a marked reduction in both the number and strength of interactions after anti–PD-1/anti-MIF combination therapy, while selectively strengthening connections with CD8+ T cells." (PMID 41122966, 2025). "Thereby, MIF exerts its effects not only within epithelial tumor cells but also in stromal fibroblasts and immune cells of the tumor microenvironment." (PMID 40835826, 2025). "MIF is a key cytokine that regulates the immunosuppressive tumor microenvironment and disrupts normal T cell function." (PMID 41472252, 2025).
tumor (continued). "Although it is possible that stromal MIF acts on either stromal or tumor cells, our data clearly demonstrate that epithelial tumor cells are the critical source of MIF required for CRC progression and maintenance." (PMID 40835826, 2025). "Interleukin-5 (IL-5) was the only cytokine linked to subretinal fluid, and multiple cytokines, such as M-CSF and MIF, were correlated with the tumor cell type." (PMID 41048959, 2025). "Tumor cells primarily played the roles of signal senders and influencers in the MIF signaling pathway, suggesting that in HCC, tumor cells can make a direct influence on immune cells." (PMID 40018995, 2025). "The tumor specificity of MIF mainly arises from its overexpression and/or chaperone-mediated stabilization, particularly in tumor epithelial cells, making it to an attractive therapeutic target." (PMID 40835826, 2025). "The macrophage migration inhibitory factor (MIF) signalling pathway, which is dysregulated to varying extents across all types of immune cells, is a key mediator by which tumour cells regulate immune cells." (PMID 39834330, 2025). "YUMMER1.7 tumor growth was significantly delayed in the MIF-KO group compared with WT controls (P = 0.0095)." (PMID 41122966, 2025). "MIF has several biological effects, including activating macrophages, improving their adherence, phagocytosis, and anti-tumor action." (PMID 40445486, 2025). "An analysis of the area under the curve (AUC) for tumor growth at day 17 revealed a significant reduction with dual anti–PD-1/anti-MIF treatment compared with the ctrl group (P = 0.01)." (PMID 41122966, 2025). "ST unveiled the spatial heterogeneity of the TME, showing that epithelial cells (tumor cells) and MIF are in close spatial proximity within tumor tissues, further supporting the critical role of MIF in regulating macrophage polarization and TME remodeling." (PMID 40867511, 2025). "Remarkably, a subset of MIF−/− mice exhibited complete tumor rejection with a significant decrease in Tregs and an increase in CD4+ and CD8+ lymphocytes." (PMID 41159021, 2025). "CCL4, CXCL8, and MIF have been shown to induce angiogenesis and immune escape of tumor cells and promote the progression of many human cancers 10-13." (PMID 40092701, 2025). "For example, neutrophils and NK cells showed significant interactions with tumour cells through pathways such as MIF‐(CD74 + CXCR4) and ANNEXIN‐(FPR1 + FPR2), which are known to modulate immune responses and tumour progression." (PMID 40099956, 2025). "Overexpression of MIF has been observed in EBV-positive NPC tumor tissues and immune lymphocytes from Hodgkin’s lymphoma patients." (PMID 41472252, 2025). "Anti–PD-1 treatment of MIF-KO or CATT5 mice further enhanced tumor responses, underscoring the additive responses of MIF and PD-1 targeting." (PMID 41122966, 2025). "B cells attracting NK cells in CD74 CD44 MIF neighborhoods was linked to better survival at 20 μm (log-HR = -1.48, p = 0.033) and 60 μm (log-HR = -1.73, p = 0.0018), indicating that NK cell presence close to B cells in these regions may contribute to an effective anti-tumor response." (PMID 40364843, 2025). "High‐resolution single‐cell transcriptomics illuminated cellular communications within the tumour ecosystem, with particular emphasis on myeloid cell interactions mediated by MIF and GALECTIN signalling networks." (PMID 40596746, 2025). "CATT5 mice had a delay in tumor establishment of about 1 week (P = 0.0047) and a reduction in tumor volume by AUC analysis at day 15 when compared with the high genotypic human MIF expresser mice (P < 0.001)." (PMID 41122966, 2025). "Based on this, cluster 4 became the only group capable of receiving signaling sent by MIF, highlighting its potential role in regulating anti-tumor immune response." (PMID 40036264, 2025).
tumor (continued). "The role of MIF in tumor progression is multifaceted, as it can either inhibit or promote tumor growth through distinct signaling pathways." (PMID 38405130, 2024). "MIF blockade using antibodies were found to inhibit tumor-induced angiogenesis, and 4-IPP inhibited neoangiogenesis." (PMID 38548753, 2024). "Among the interaction molecular pairs, tumour invasion‐related pairs, including CD74_MIF, SPP1_CD44, were enriched among macrophages and MYH11+ CAFs." (PMID 39294858, 2024). "Increased levels of tumor-expressing and circulating MIF, DDT, and CD74 have been detected in early- and late-stage cervical cancer and have been linked to lymphatic metastasis and up-regulation of E-cadherin and vimentin." (PMID 38732068, 2024). "Elevated serum MIF levels in NSCLC predict worse overall and progression-free survival, and co-expression with CD74 correlates strongly with enrichment of tumor-associated CXC chemokines and tumor vascularization." (PMID 38732068, 2024). "Within the context of HCC, MIF assumes a tumor-promoting role by enhancing proliferation and inhibiting apoptosis, a mechanism likely facilitated by the interaction between MIF and ERK1/2." (PMID 38238845, 2024). "The abundance of MIF+ neoplasm showed potential predictive value for OS in the chemotherapy cohort (HR >1, p < 0.05)." (PMID 38946232, 2024). "Previous research has reported that MIF deficiency and treatment with the small-molecule MIF inhibitor 4-IPP contribute to the restoration of immunosuppressive tumor progression of tumor-associated macrophages to M1-like polarization characteristics." (PMID 39735553, 2024). "Previous studies have shown that MIF is involved in multiple immune processes and mediates immune escape leading to tumor metastasis." (PMID 38200479, 2024). "The expression of the receptors CXCR4 and CD74 was markedly increased in tumor cells, suggesting activation of the MIF signaling pathway in tumors." (PMID 38191424, 2024). "MIF is highly expressed by GBM cells and higher levels of MIF are associated with increased cancer grade as well as poor prognosis and tumor recurrence." (PMID 38178143, 2024). "In other studies related to HCC, the expression of MIF was higher in HCC tissues than in healthy or adjacent non-tumor liver tissues." (PMID 38638429, 2024). "Co-expression of MIF and its putative receptor CD74 in NSCLC is associated with greater tumor vascularity and greater levels of angiogenic CXC chemokines." (PMID 38685050, 2024). "The elevated levels of granzyme B+ B cells in tumor samples resulted from tumor cell chemotaxis through the MIF- (CD74 + CXCR4) signaling pathway." (PMID 38386050, 2024). "MIF is able to promote cellular processes related to tumorigenesis such as cell cycle progression, tumor growth, blockage of apoptosis, induction of angiogenesis and tumor spread." (PMID 38178143, 2024). "Given the importance of MIF in driving many tumor-accelerating phenotypes, MIF represents a promising therapeutic target for primary CNS tumors." (PMID 39233830, 2024). "The involvement of MIF in angiogenesis in different tumor types is consistent with our quantifications of a striking effect on tumor vasculature in our in vivo model." (PMID 38548753, 2024). "In tumour cells, the MIF pathway was triggered by autocrine signals and stimulates the production of cytokines, chemokines, and angiogenic factors, which lead to tumour growth, increasing its aggressiveness and metastatic potential." (PMID 38633247, 2024). "For the MIF signaling pathway, the primary sender of MIF signals is the C2-E.T cluster, while the most crucial receiver of signals is the C7-Tumor cluster." (PMID 38191424, 2024). "Pre-clinical and clinical research in patients with NB consistently shows that MIF possesses characteristics that promote tumor growth in NB." (PMID 38601081, 2024).
tumor (continued). "MIF inhibition decreases tumor growth in murine ESCC models, concordant with patient studies correlating MIF serum and tumor enrichment with tumor dedifferentiation, vascular invasion, lymph node metastases, and worse survival." (PMID 38732068, 2024). "Studies have shown MIF signaling pathway inhibits tumor apoptosis and promotes angiogenesis by activating downstream PI3K/Akt signaling pathway." (PMID 38702814, 2024). "This refined analysis confirms that MMP7+ tumour cells exhibit distinct communication patterns with immune cells, particularly through the MIF signalling pathway." (PMID 39187937, 2024). "When compared with normal group, CD56bri_CCL5 cells in tumor demonstrated an increased interaction weight with macrophage cells through the MIF-(CD74+ CD44) ligand-receptor pair." (PMID 38552055, 2024). "CKS1B+ neoplasm is at the initial stage of development, gradually decreasing over time, whereas MIF+ neoplasm is at the terminal stage, increasing as time progresses." (PMID 38946232, 2024). "Taken together, these findings highlight the influence of tumor cells chemotaxis on GrB+ B cells through the MIF- (CD74 + CXCR4) signaling pathway." (PMID 38386050, 2024). "CD36 + lpmCAFs can recruit CD33 + MDSCs through a macrophage migration inhibitory factor (MIF)-dependent pathway, thereby mediating tumor immune evasion." (PMID 38679698, 2024). "MIF exerts its pro-tumor effects by modulating the immunosuppressive TME, mainly via regulating the CD74 signaling in macrophages and dendritic cells (DCs)." (PMID 38685050, 2024). "Using the CellChat R package, intercellular communication analysis revealed that tumor-associated macrophages (TAMs) interact with other cells in the PCa TME primarily through MIF - (CD74+CXCR4) and MIF - (CD74+CD44) ligand-receptor pairs." (PMID 38663915, 2024). "Elevated levels of MIF are found in tissue and serum samples from patients with osteosarcoma and are correlated with increased tumor size, pulmonary metastases, and worse survival." (PMID 38732068, 2024). "In liver cancer, tumor cells promote the recruitment and expansion of MDSCs within the TIME by releasing hypoxia-inducible factor 1-alpha (HIF-1α) and tumor-associated cytokines, such as IL-6, IL-1β, GM-CSF, G-CSF, VEGF, MCP-1, and MIF." (PMID 39596288, 2024). "Our previous studies also revealed that bufalin can regulate the polarisation of macrophages by targeting the SRC-3/MIF pathway, leading to anti-tumour effects." (PMID 38268819, 2024). "MIF signaling pathway found in tumor metabolism has been substantiated to inhibit various immune-cell activities including cellular infiltration, maturation, and antigen presentation." (PMID 38948053, 2024). "Compared to FABP6+ tumor cells, normal tissues were found to lack the MIF-related pathway in our analysis of cellular communication output signal patterns." (PMID 38277205, 2024). "Data were also corroborated by the analysis on high cfDNA CAFs lysates, confirming the over-expression of MIF, SerpinE1, and IL17E, strictly associated to the high tumor burden (p < 0.05), pinpointing CAFs as potential source of SerpinE1." (PMID 39609411, 2024). "Analysis of the TCGA-LIHC cohort revealed significant upregulation MIF expression within tumor tissues." (PMID 38927691, 2024). "Inflammatory cytokines, such as interleukin (IL)-1, IL-6, IL-10, tumor necrosis factor-α, macrophage migration inhibitory factor, and transforming growth factor-β, are involved in tumor initiation and progression." (PMID 38267838, 2024). "In head and neck squamous carcinoma, the HIF-1α–MIF axis contributed to the recruitment of myeloid (CD11b + -Gr-1 +) cells to enhance tumor growth and angiogenesis." (PMID 38685050, 2024). "We found that signals such as SPP1 and MIF were more active in tumor tissues, indicating potential oncogenic roles of macrophages." (PMID 39850883, 2024). "It has also been revealed that high expression of MIF is closely related to tumor progression and metastasis." (PMID 39464891, 2024).